IL1B (interleukin 1 beta)
Diseases named in the same sentence as IL1B in open-access papers (continued):
Sharing a sentence is not in itself a finding about the gene and the disease.
Stroke (continued). "During the acute period after stroke, microglia secrete pro-inflammatory cytokines IL-6, TNF-α, and IL-1β, which can induce secondary cytotoxicity." (PMID 33479185, 2021). "To understand the effect of HDAC1 in pathologic mechanism of stroke, we examined the levels of ROS, LDH, IL-1β, and TNF-α on day 3 after stroke." (PMID 34381129, 2021). "On the other hand, pretreated groups (@, @@) (BBR 100 mg/kg, nano BBR 100 mg/kg (p < 0.01), 75 mg/kg, and 50 mg/kg (p < 0.05)) showed a significant reduction in TNF-α, IL-1B, and MDA levels compared to the stroke group." (PMID 34600570, 2021). "IL1B, IL10, TNF, IL6, and ICAM1 are closely related to the inflammatory response after stroke, among which IL-10 is an important anti-inflammatory factor, while L1B, TNF, and IL6 are proinflammatory factors." (PMID 33727944, 2021). "Based on the 95 crossover genes identified, PPI network analysis uncovered six core genes including MMP9, MAPK3, PTGS2, JUN, IL1B and TNF likely linking the activity of luteolin to effective stroke control." (PMID 34898370, 2021). "Second, RIPC has been shown to decrease the expression of HIF-1α and HIF-2α in the ischemic brain and to decrease the protein levels of pro-inflammatory cytokines IL-1β and IFN-γ in both the blood and brain 48 h post-stroke." (PMID 32210788, 2020). "One month after LPS treatment, the priming of LPS induced significantly higher IL-1β, IL-6, and TNF-α production 24 h after the subsequent stroke, and infarct size was also exacerbated by the LPS priming." (PMID 33013828, 2020). "Our data showed that RIPC reduced the levels of pro-inflammatory cytokines IL-1β, IL-6 and IFN-γ in the blood, and IL-1β and IFN-γ in the brain in aged rats 48 h post-stroke, while the changes that were neutralized by the HIF inhibitor." (PMID 32210788, 2020). "Proinflammatory microglia prevail in the acute phase following stroke, along with enhanced expression of tumor necrosis factor‐alpha (TNF‐α), interleukin (IL)‐1β, IL‐12, and inducible nitric oxide synthase (iNOS)." (PMID 32757264, 2020). "RIPC reduced the levels of IL-1β, IL-6 and IFN-γ in the peripheral blood and the levels of IL-1β and IFN-γ in the ischemic brain 48 h post-stroke." (PMID 32210788, 2020). "The iNOS‐expressing microglia/macrophages secrete pro‐inflammatory cytokines such as interleukin‐1 beta (IL‐1β) and tumour necrosis factor alpha (TNF‐α), which subsequently exacerbate brain injury in stroke." (PMID 32713053, 2020). "Pro-inflammatory cytokines, such as tumor necrosis factor alpha (TNF-α), interleukin 6 (IL-6), interleukin 1 beta (IL-1β), and monocyte chemoattractant protein-1 (MCP-1), were significantly increased in the CLEC14A-KO mice after stroke." (PMID 32019570, 2020). "IL-6, interleukin 1β (IL-1β) and tumor necrosis factor-alpha (TNF-α) are the major proinflammatory cytokines that provoke and aggravate an inflammatory response after stroke." (PMID 33192985, 2020). "In stroke, the inflammatory factors secreted by activated microglia (M1), such as TNF-α, IL-1β, and IL-6, are significantly elevated." (PMID 32733433, 2020). "We observed significantly higher levels of proinflammatory cytokines IL-1β, IL-6, and TNF-α in plasma of stroke mice and the BR therapy decreased the levels of these cytokines in plasma." (PMID 32843630, 2020). "To verify the anti-inflammatory function of Gen after reproductively senescent stroke, we evaluated inflammatory factors, including TNF-α, IL-1β, IL-18, and IL-6 in ischemic penumbra area 24 h after reperfusion." (PMID 32625078, 2020). "At least one mechanism likely involves IL-1β upregulation of pentraxin 3 (PTX3), a marker of stroke." (PMID 31293586, 2019). "To understand the anti-stroke mechanism of QKL, we determined the protein expression levels of NLRP3, ASC, pro-caspase-1, cleaved-caspase-1, pro-IL-1β and cleaved-IL-1β in the brain tissue of rats." (PMID 31747940, 2019).
Stroke (continued). "Pro-inflammatory microglia dominate during the acute phase after stroke and are characterized by increased tumor necrosis factor alfa (TNF-α), interleukin (IL)-1β, IL-12, and inducible nitric oxide synthase (iNOS) expression amongst others." (PMID 31379859, 2019). "The proinflammatory cytokine production of interleukin-1β (IL-1β), IL-6, and interferon-γ (IFN-γ) in the brain was upregulated in the vehicle-treated WT and AHRflx/flx mice at 48 h after stroke." (PMID 31606043, 2019). "Here, we also found that levels of IL-1β, IL-1RA, IL-10, IL-13, IL-15, Flt-3L, Fractalkine, EGF, G-CSF and GM-CSF were lower in the severe stroke group." (PMID 31164999, 2019). "The three major proinflammatory cytokines are interleukin 1β (IL-1β), tumor necrosis factor-alpha (TNF-α), and interleukin-6 (IL-6) that provoke and aggravate an inflammatory response after stroke." (PMID 31291966, 2019). "Similar to the effect of miR155, an antagomir for miR210 decreased expression of proinflammatory cytokines IL6, TNFα, IL1β, CCL2, and CCL3 reducing the neurological impairment, putting miR210 as potent regulator of inflammation during stroke recovery." (PMID 31543756, 2019). "Regarding pro-inflammatory cytokines, it has been described that blocking TNF-α and IL-1β confers neuroprotection in SCI and stroke models." (PMID 31186006, 2019). "We found that TMF-treated WT and AHRcKO mice showed significantly attenuated IL-1β, IL-6, and IFN-γ production in the brain after stroke." (PMID 31606043, 2019). "Lactadherin treatment significantly increases anti-inflammatory factor (IL10) expression in ischemic brain and decreases IL1β expression in plasma compared to PBS and BDMP treated stroke mice, respectively." (PMID 31993045, 2019). "Our data show that BDMPs increase the infiltration of leukocytes, microglia/macrophages and neutrophils, and the expression of immune factors IL1β, IL6, and TNF-α in the IBZ of stroke mice." (PMID 31993045, 2019). "Canakinumab, a human anti-IL-1β monoclonal antibody, is FDA-approved for arthritis, but remains to be tested in stroke patients." (PMID 31544811, 2019). "The levels of pro-inflammatory cytokines (e.g., IL-6, IL-1β, and TNF-α) were all induced by stroke in control mice." (PMID 31771656, 2019). "We then isolated EV from the serum of 16 aged-matched donors and 16 stroke samples and analyzed the protein levels of caspase-1, ASC, IL-1β, and IL-18 in these isolated EV with the Simple Plex technology." (PMID 30233311, 2018). "Expression levels of IL-1β and TNF-α mRNA were elevated at days 1 and 2 after stroke in the vehicle group, but TPPU treatment significantly attenuated expression at day 2 (p < 0.05; n = 6 rats per group)." (PMID 29588470, 2018). "Previous studies in animal models and in stroke patients have shown that continued production of cytokines such as IFNγ, TNFα, IL11, IL-1β, IL-1ra and IL-6 induces and maintains the M1 polarization state." (PMID 30584250, 2018). "In summary, the major effects of MLC901 are the reduction of neutrophil recruitment, the reduction of microglia activation and the reduction of pro-inflammatory mediators (TNFα, IL6, IL1β, CCL2) production induced by stroke." (PMID 30584250, 2018). "Consistent with this, expression of IL-1β and TNF-α were significantly reduced by BAY 60-2770 treatment 4 h post-stroke." (PMID 29423274, 2018). "These are partly verified by our findings revealing NF-κB activation and the expression of target genes, including TNF-α, IL-1β, IL-6, iNOS, and COX-2, in KO stroke mice." (PMID 30622459, 2018). "In our investigation, results from tumor necrosis factor (TNF-α), interleukin 1 beta (IL-1β) and interleukin 6 (IL-6) assessment demonstrated that of Danshensu or HSYA treatment has an anti-inflammatory effect for stroke." (PMID 29383171, 2017). "IL-17A, produced mainly by activated Th17 cells, can induce the secretion of a variety of stroke-related cytokines, such as IL-6, TNF-α, IL-1β, CXCL1 and CXCL8." (PMID 29262579, 2017).
Stroke (continued). "In contrast, macrophages are also a major source of IL-1β, TNF-α and ROS, adding to further inflammatory insult after stroke." (PMID 26742037, 2016). "Thus here, we examine the acute effects of IL-1β on neural activity and cortical haemodynamics in response to mechanical stimulation of the barrel cortex to investigate whether IL-1β exacerbates stroke and other brain injuries by negatively impacting upon neurovascular coupling." (PMID 27557843, 2016). "Sieber and collegues previously showed that increases of TNFα, IL-1β, MIP-1α, MCP-1, and IL-6 are attenuated 7 days following stroke in aged C57BL/6 mice, and that older mice have smaller infarct volumes." (PMID 27600707, 2016). "Pro-inflammatory mediators (such as IL-6, IL-1β, and TNF-α) contribute to expanding the area of brain injury in the context of stroke." (PMID 27549161, 2016). "In BALB/c mice at 1 week post-stroke G-CSF, IP-10, KC, MCP-1, MIP-1α, and MIP-1β were increased, and levels of IL-1β, IL-10, and IL-13 were decreased compared to sham mice." (PMID 27600707, 2016). "Previous studies showed it has a strong inhibitory effect of IL1β, IL6, IL10, TNF and other circulating cytokines, and suggested a potential therapeutic for stroke patients." (PMID 27672514, 2016). "Stroke subjects also showed higher cytokine plasma levels such as TNF-α (28.2 ± 29.3 vs 12.3 ± 4.5 pg/mL; P = 0.0001), IL-1β (7.9 ± 2.6 vs 4.7 ± 1.6 pg/mL; P = 0.0001) and IL-6 (8.2 ± 2.4 vs 4.2 ± 1.5 pg/mL; P = 0.0001) compared to controls." (PMID 25997053, 2015). "In our study, aLA treatment significantly decreased the expression of major inflammatory cytokines that play an important role during the acute phase of stroke such as TNF-α, MIP1, Iba-1, and IL-1β in RT-PCR." (PMID 25761600, 2015). "Consistent with previous stroke studies, we also observed an increase in several brain inflammatory cytokines including IL-6, TNF-α, IL-1β in the ischemic hemisphere of vehicle treated animals." (PMID 24618563, 2014). "In SHRSP, fed a high-salt diet, rosuvastatin treatment significantly delayed the onset of stroke and attenuated the transcription of inflammatory biomarkers (MCP-1, TGF-β1, IL-1β, and TNF-α)." (PMID 23431245, 2013). "Clinical and experimental data showed a detrimental role of inflammatory cytokines in injured brain, and inhibition of IL-1β and TNF-α activity with neutralizing antibodies or soluble receptors decreased neuronal damage in animal models of stroke." (PMID 22806180, 2012). "Inflammatory conditions, such as IL-1β level in plasma and IL-1β signal-related gene expressions in CVECs, are greater in SHRSP compared with WKY or SHR prior to the onset of stroke." (PMID 23326018, 2012). "In SHRSP fed a high-salt diet, rosuvastatin treatment significantly delayed the onset of stroke and attenuated the transcription of inflammatory biomarkers (MCP-1, transforming growth factor-β1, interleukin (IL)-1β, and tumor necrosis factor-α (TNF-α))." (PMID 23326018, 2012). "Levels of the pro-inflammatory cytokines IL-1β, TNF-α, and IFN-γ were significantly elevated in the ischemic hemisphere considered as hallmarks of inflammation after stroke." (PMID 23028794, 2012). "IL1β is a potent inducer of IL1 receptor antagonist (IL-rn), which significantly reduces damage in response to stroke and, notably, is upregulated in our microarray (Lt)." (PMID 21999375, 2011). "Inflammatory cytokine and chemokine levels, including IL6, IL1β, MCP-1 and TNFα are elevated in the circulation following stroke." (PMID 21999375, 2011). "Second, although the TNF-α/IL-6/IL-10 triad is central to stroke inflammation, additional mediators such as interferon-γ, MCP-1, and most notably, the critical driver IL-1β, along with cellular actors like microglia subtypes and peripheral leukocytes, are not explicitly modeled." (PMID 41557608, 2026).
Stroke (continued). "Immunological and inflammatory biomarkers, including IL-1β, IL-6, TNF-α, IL-10, IL-8, IL-17, and CRP, have become indispensable tools in stroke research, offering insight into how the immune system shapes both the extent of brain injury and the trajectory of recovery." (PMID 40869247, 2025). "We found significantly increased activation of microglia and increased levels of the inflammatory cytokine IL-1β in the hippocampus of mice with stroke but not in those of mice subjected to TFIF alone." (PMID 40026365, 2025). "The fold change in IL-1β concentration quantified by ELISA tended to be highest at t2 and lowest at t3 in the stroke cohort, but no comparisons of fold changes were significant between the groups." (PMID 41373643, 2025). "Other positive effects of anthocyanin preconditioning in inducing stroke have also been mentioned, such as improving spontaneous activity and memory, and reducing the levels of molecules involved in the inflammatory response such as TNF-a, IL-1B, and IL-6." (PMID 40724240, 2025). "Similarly, pro-inflammatory cytokines IL-1β, IL-6 and TNF-α were significantly upregulated in the Stroke group relative to Sham controls (p < 0.001)." (PMID 41388741, 2025). "Experimental studies in mice lacking IL-1α and IL-1β showed they exhibit smaller infarct volumes after middle cerebral artery occlusion, underscoring the cytokine’s neurotoxic role in stroke pathophysiology." (PMID 40869247, 2025). "IL-1β and CCL2 have a promoting effect on post-stroke inflammation." (PMID 40948793, 2025). "Despite the absence of phase III efficacy data, IL-1β remains a strong candidate for targeted intervention and a valuable biomarker reflecting acute neuroinflammatory activation after stroke." (PMID 40869247, 2025). "Furthermore, hNSC transplantation reduces infarct size and proinflammatory factor (TNF-α, IL-6, and IL-1β), matrix metalloproteinase-9 (MMP-9), and MMP-3 expression in aged stroke mice." (PMID 37728582, 2024). "Moreover, we identified attenuated Nrf2/HO-1 axis activation led to increased CD68/IL-1β and suppressed CD206 expression in MG, resulting in aggravated inflammatory MG in MG-specific Nrf2 knockdown mice after stroke." (PMID 39469715, 2024). "Both the inhibition of AIM2 and NLRP3 prevented inflammasome activation in the CCA plaque after stroke, with greater efficacy of the AIM2 inhibitor, whereas only the AIM2 inhibitor significantly prevented the post-stroke increase in IL-1β levels in the CCA plaque." (PMID 39112714, 2024). "Therefore, investigation the prognostic value of markers in the NETs/AIM2 inflammasome axis, such as MPO-DNA, PAD4, HMGB1, C1q, AIM2, ASC, Caspase-1, IL-1β, IL-6 and IL-8, in LAA stroke patients is a meaningful endeavor." (PMID 39737165, 2024). "Stroke-induced alterations in microglia and astrocytes emerge as critical in PSD evolution, modulating neurotransmitter dynamics, neuronal viability, and cytokine release, including pro-inflammatory IL-1β, IL-6, TNF-α, and anti-inflammatory IL-10." (PMID 38377025, 2024). "Notably, at earlier time points within 24 h post-stroke, microglial M1 polarization is significantly enhanced, accompanied by elevated levels of pro-inflammatory cytokines like TNF-α, IL-1β, IL-6, and chemokines C-C motif chemokine ligand 2/3 (CCL2/3)." (PMID 39633709, 2024). "In our experiment, the post-surgical assessment of proinflammatory cytokines, including IL-1β, IL-6, and TNF-α in the hippocampal tissue, revealed that the inflammatory response in the CNS of mice with stroke was markedly higher than that in mice undergoing sham operations." (PMID 39758888, 2024). "When stroke occurs, the NF-κB inflammatory signaling pathway is activated to stimulate the phosphorylation of P65 protein to p-P65, and then p-P65 enters the nucleus to further induce the release of inflammatory factors including TNF-α, IL-1β and IL-6 etc.." (PMID 38756375, 2024).
Stroke (continued). "Interleukins such as IL-1β, TNF-α, and IL-6 can help mitigate the inflammatory response and improve outcomes in stroke patients, which could be another immunomodulation target." (PMID 39633897, 2024). "Moreover, we demonstrated that neutralization of systemic IL-1β prevents MMP activation and plaque degradation after stroke." (PMID 39112714, 2024). "Yang and coworkers also reinforced the role of IL-6 and other cytokines like IL-1β and TNFα in disruption of blood–brain barrier (BBB), leading to neurological degeneration in such diseases as Alzheimer’s disease (AD), stroke, multiple sclerosis (MS), and posttraumatic brain injury (TBI)." (PMID 38093175, 2023). "However, the effects NLRP3 inflammasome activation and pyroptosis after stroke were attenuated by IPC, which decreased the expression of NLRP3, ASC, cleaved caspase 1, and GSDMD-N and reduced the production of IL-1β and IL-18." (PMID 37371374, 2023). "Patients with myocardial infarction and a CRP of ≥ 2 mg/l receiving IL-1β-specific neutralizing antibodies presented significantly lower rates of recurrent cardiovascular events and non-fatal stroke." (PMID 37212886, 2023). "In this study, we report for the first time that stroke in T2DM mice induces earlier and higher inflammatory factor, cytokine, and acute phase response protein expression such as SAA, NLRP3, IL-1β, IL-6, TNFα, and TLR4 in the liver compared to heart and kidney." (PMID 36968490, 2023). "Similarly, herein, we revealed that the IL‐1β, TNF‐α, IL‐6 and IFN‐γ mRNA contents enhanced after the development of ischemia in tMCAO stroke rats, whereas, these expressions were diminished after engeletin treatment." (PMID 37132060, 2023). "Patients with an NIHSS score>7 showed a significantly higher level of IL-1β andlowerexpression of Malat1 relative to other patients who had an NIHSS score<6 while wecouldn’tdetect a significant negative correlation between stroke severity and VitD level." (PMID 38974129, 2023). "In addition, our previous study found that inhibition of LMP2 decreased the protein levels of IL-1β and TNF-α in rat stroke model." (PMID 36978132, 2023). "In addition to IL-1β and TNF-α, IL-6 is also a pleiotropic cytokine that is involved in stroke, but its function is still controversial." (PMID 37951917, 2023). "We identified Il-1β, Ccl2, Cybb, Wnt9b, as well as some pathway-specific genes such as S100a8 and S100a9 (IL-17 signaling) among the common pro-inflammatory and signaling molecules whose expression was affected by higher TMAO levels in post-stroke animals." (PMID 37175797, 2023). "Further, young male mice had significantly higher expression of pro-inflammatory and chemotactic cytokines including Cxcl2/Mip2a (P = .0171), but not Cxcl9 and Il1b, after stroke, which was not seen in young females." (PMID 37910478, 2023). "Of them, Interleukin-1 beta (IL-1β) and tumor necrosis factor alpha (TNF-α) appear to play a particularly important role in stroke pathology, since they have a damaging effect on neuronal and glia cells and enhance the release of proinflammatory prostaglandins." (PMID 36358492, 2022). "In the Canakinumab Anti-Inflammatory Thrombosis Outcome Study, targeting IL-1β benefited patients with previous myocardial infarction (MI) in the view of non-fatal MI, non-fatal stroke, and cardiovascular death." (PMID 36017088, 2022). "Recently, Hettwer and colleagues also reported an involvement of IL‐1β and the NLRP3‐inflammasome pathway in atheroprogression, which is a mechanism of likely relevance also for the inflammatory response after stroke." (PMID 35971650, 2022). "The one‐way ANOVA analysis revealed that IL‐1β and IL‐6 transcripts were upregulated in response to stroke (p < 0.001), while mRNA expression of IL‐10 did not change relative to sham (p = 0.20)." (PMID 35715988, 2022). "Our previous report showed increased levels of IL‐1β and NLRP3 expression after ischaemic stroke, but NLRP3 deficiency or inhibition did not improve stroke outcome." (PMID 35137954, 2022).